CD74 (CD74 molecule)
Diseases named in the same sentence as CD74 in open-access papers (continued):
Sharing a sentence is not in itself a finding about the gene and the disease.
cancer (continued). "Thereby, CD74 is critically involved in MIF-driven immune cell recruitment and activation of a variety of cellular responses, including cell proliferation and cell metabolism that have been found to play a role in cancer, metabolic and ischemic heart disease." (PMID 38992165, 2024). "CD74 and MIF together encourage cell proliferation and inhibit cell death, and MIF’s role in inflammation has been recognized as an important potential player in cancer initiation and development." (PMID 38730725, 2024). "Interestingly, we found that CD74-derived peptide synergizes with AKT inhibitor to activate cleaved caspase 3 and enhance early apoptosis in MDA-MB-436 cancer cells." (PMID 39056676, 2024). "Our results uncover a principle in AML disease suggesting cancer stem cell-driven regeneration is not solely cell autonomous in nature and involves other complex cellular elements exemplified by CD74+CD68+ RECs." (PMID 38582086, 2024). "Here, we analyzed gene expression pattern of cancer patients and/or patient-derived xenograft (PDX) models and found that mRNA and protein levels of CD74 are highly expressed in TNBC and correlated with cancer stem cells (CSCs) and epithelial–mesenchymal transition (EMT) properties." (PMID 39056676, 2024). "Therefore, it is important to design prospective studies that examine CD74 and MIF as biomarkers of ICB response or irAE development across a broad range of cancers, irAEs, and ICB treatments to determine their generalizable use in human subjects." (PMID 38730725, 2024). "Remarkably, MIF-(CD74+CD44) signalling between hepatocytes and T/NK and macrophages, which mediates immunosuppressive effects that have previously been illustrated for promoting cancer progression." (PMID 36860314, 2023). "Thirdly, the heightened transcript levels of these chosen proteins were associated with diminished patient survival rates (with statistical significance at p < 0.05 in a 50% low vs. 50% high comparison) in cases of PDAC and other cancer types, with the exception of LZM and CD74." (PMID 37894284, 2023). "Notably, we found an increased signaling of MIF-(CD74+CD44) in T-ICC between malignant cells and TAMs or T cells, which has been well documented to promote cancer progression." (PMID 35558087, 2022). "The role of the interaction between CD74 and MIF has been revealed in different types of cancers." (PMID 34540893, 2021). "Alternatively, that more immune cell-infiltrated cancers have more of their CD74 mRNA contributed by immune cells and that this results in a larger survival difference, rather than the CD74 expressed endogenously in cancer cells." (PMID 34944801, 2021). "However, cancer cell apoptosis genes such as CDK5RAP1 and BCL2 or iron-sulfur clusters, which protects cancer cells against oxygen to damage a class of iron-dependent proteins such as NSF1, are significantly higher in the “CD74 low” samples." (PMID 33327409, 2020). "CD74 mRNA in brain, retina, lung, and lymph nodes displayed higher levels than in the matched cancer tissues, while FCGR2A mRNA in thyroid, lung, kidney, peritoneum, and lymph node tissues displayed higher levels than in the matched cancer tissues." (PMID 31992246, 2020). "Inhibition of MIF expression (by anti-MIF or anti-CD74 antibodies or chemotherapy) or COX expression (by indomethacin) has shown encouraging results, which may hinge upon the type of cancer." (PMID 29247872, 2017). "The morphogenetic BMP signaling (BMP6 and INHA), the pro-inflammatory JAK/STAT pathway and CD74, a pro-inflammatory component in terms of infiltrating macrophages, resulted in discriminating between cancer and non-cancer samples." (PMID 28216608, 2017). "A rapid internalization of CD74 (106 to 107 molecules/cell/day) in a wide range of cancer cells, which is not affected by the binding of the mouse monoclonal anti-CD74 antibody LL1, give rise to several therapeutic approaches." (PMID 25304249, 2014).
cancer (continued). "This review synthesizes emerging evidence that CD74 functions as a “master regulator” of antigen presentation in cancer, integrating its canonical chaperone role with its noncanonical role in transcription regulation and in signaling via macrophage migration inhibitory factor." (PMID 41597203, 2026). "Furthermore, ligand–receptor analysis showed preferential interactions of C5AR1-RPS19 and CD74-MIF pairs between GTSE1+ OB cells and CREB3L1+ CB cells in metastasis, which could promote cancer cell growth and metastasis." (PMID 40831537, 2025). "Next to its classical role in MHC II-mediated antigen presentation, CD74 was identified as a high-affinity receptor for macrophage migration inhibitory factor (MIF), a pleiotropic cytokine and major determinant of various acute and chronic inflammatory conditions, cardiovascular diseases and cancer." (PMID 38992165, 2024). "Notably, we identified several key ligand-receptor pairs in TNChigh cancer cells and immune cells, including NECTIN2-TIGIT, MIF-(CD74+CD44), MDK-NCL, LAMB3-CD44, COL1A2-CD44, COL1A1-CD44, CD99-CD99, APP-CD74, and GZMB-PARD3 were identified in TNChigh cancer cells and immune cells." (PMID 38711034, 2024). "CD74 status was not significantly correlated to cancer cell-positive lymph nodes." (PMID 34944801, 2021). "We find that the genes specifically expressed in the supratentorial tumors from these publications (such as HLA-DRA, LYZ, CD74, F13A1, and TRIM22) tend to be expressed in cells within the microglia-type cluster, whereas the infratentorial tumors have higher expression of cancer cell-related genes." (PMID 31427603, 2019). "MIF inhibitors, particularly when acting on the MIF/CD74 axis, could be a very attractive strategy for cancer therapeutic intervention due to the nonphysiologic enzymatic activity of the cytokine that is evolutionary well-conserved." (PMID 28114961, 2017). "The absence of CD74 in 226LDM cells was anticipated, since CD74 has, so far, only been detected in antigen-presenting cells, including B cells, monocytes, macrophages, dendritic cells and Langerhans cells, and in inflammatory cells, including those detected in cancers." (PMID 29190904, 2017). "The expression levels of CXCL12, THBS1, PPBP, GZMB, CD74, and UNC93B1 were higher in the cancer group than in the normal group." (PMID 36211454, 2022). "An M2 macrophage polarization was also compatible with the observed CD74 enriched expression pattern and the elevated levels of macrophage migration inhibitory factor (MIF) cytokine in the cancer specimens (data not shown)." (PMID 28216608, 2017).
infection (51 papers, 2009 to 2026). The state of being infected such as from the introduction of a foreign agent such as serum, vaccine, antigenic substance or organism. "CpG sites linked to Ccl7, Ccl9, Cd74, and Casp8 exhibited the lowest methylation in uninfected samples but increased on Day 1 of infection and then decreased gradually." (PMID 40170749, 2025). "Cell-to-cell communication analysis further indicated that the interaction between the epithelial, vascular endothelial, pDCs, and fibroblast subsets, except for COL3A1 fibroblasts, was enhanced mainly via CD74/(COPA or MIF) receptor ligands after infection." (PMID 41843736, 2026). "In contrast, Class1 was dominated by viral-infection annotations and antigen presentation (e.g., HLA-DRB1/DQB1/C, CD74, CTLA4, GZMB, PRF1), consistent with HIV-associated immune activation." (PMID 41394852, 2025). "When the piglets were infected with G. parasuis, the mRNA expression levels of MIF and CD74 in the spleen were significantly reduced (p < 0.001), while levamisole enhanced the MIF and CD74 mRNA levels in the spleen compared to the infection group (p < 0.01)." (PMID 40427533, 2025). "The expressions of Ccl7, Ccl9, Cd74, and Casp8 were highest in uninfected samples but decreased on the first day of infection and then gradually increased." (PMID 40170749, 2025). "Doses of 25–100 mg/kg baicalin also increased the mRNA expression levels of MIF and CD74 in the spleen compared to the infection group (p < 0.05)." (PMID 40427533, 2025). "We also analyzed PTEC subsets and found that CD74+ PTECs exhibited remarkably enhanced functional scores in terms of infection, phagocytosis and necrosis among all subgroups, which was even more pronounced in Aoah-/- mice." (PMID 38904010, 2024). "Markers of B cells (Cd19), T cells (Cd3g), and antigen presentation (Cd74 and Cd83) were elevated in aged lungs at day 3 post-infection." (PMID 37852965, 2023). "So antibiotics cause damage to the organism after regulating intestinal microorganisms or after infection, activating two factors, CD74 and SAA2, and activating a large number of genes and cells at the same time." (PMID 37193034, 2023). "We used the rescued strain rSczy3 to infect CEKs and performed qRT-PCR to evaluate the relative expression levels of CTSL, CTSB, Abl1, Abl2, IFITM3, ADAM17, TMPRSS2, NRP1, and CD74 at 12 and 24 h post-infection." (PMID 37376546, 2023). "A detailed analysis of CD74+ T cell populations revealed that most of them had a central memory phenotype early in infection, while cells with an effector and effector memory phenotype arose later during infection." (PMID 37946732, 2023). "The levels of endogenous CD74 expression increased at 1 h after EV-D68 infection and decreased with the extension of infection time." (PMID 37409968, 2023). "Western blot analysis showed that WT CD74 was cleaved after EV-D68 infection or Flag-3C ectopic expression, producing the same CD74 cleavage (lanes 3 and 7)." (PMID 37409968, 2023). "Later during infection, T cell populations with EM and effector phenotypes also vigorously enhanced the expression of CD74." (PMID 37946732, 2023). "All identified MHCII proteins, which typically present exogenous antigens, as well as the invariant chain (CD74), were strongly elevated throughout the clearance phase of infection, with a peak Log2FC of between 3.1 and 4.9." (PMID 35100877, 2022). "Expression of the CD74 co-receptor was found on ~50% of both ILC2s and peritoneal macrophages, and although downregulated by infection in the former population, many ILC2s expressed the combination of CXCR4 and CD74." (PMID 35288645, 2022). "During L. monocytogenes infection, expression and MFI of CD74 increased on d1 p.i., but then decreased to the level observed in uninfected animals as infection progressed." (PMID 36010615, 2022). "At 3 days post infection (dpi) the cells were FACS-sorted according to the cell-surface levels of CD74 and MHCII." (PMID 31967545, 2020).
infection (continued). "There are two alternative explanations for the inverse-correlation between viral transcript levels and CD74 cell-surface levels, several days post infection with HCMV." (PMID 31967545, 2020). "An earlier study by our group, using human placental explants, demonstrated that MIF and its receptor (CD74) were upregulated in response to T. gondii infection, thus playing an important role in controlling infection in a gestational age-dependent manner." (PMID 29867817, 2018). "In contrast, only a few immunity-related mRNAs encoding chemokines (Cxcl10, Cxcl1, Ccl2) and the invariant chain (CD74) were up-regulated in multiple host cell types after infection." (PMID 28775382, 2017). "This analysis also highlighted a central role for inflammation and infection, evidenced by networks containing genes such as CD74, S100A9, and THY1." (PMID 19513121, 2009). "Among the signals from macrophages to LZ GC B cells and memory B cells, the Lgals9-Ighm/Cd45 signaling showed a greater enhancement by PCV2 infection, while those signals that were originally stronger in the control group, such as Ptprc-Cd22, Cd52-Siglecg, and App-Cd74, were weaker." (PMID 41011514, 2025). "The data demonstrated that the G. parasuis inhibited the positive protein expression level of CD74 in the spleen compared to the control group, while levamisole and 25–100 mg/kg baicalin promoted the positive protein level of CD74 in the spleen compared to the infection group (p < 0.05)." (PMID 40427533, 2025). "It is demonstrated that parasites express MIF-like genes and could interact functionally with the MIF receptor (CD74) acting as evasion mechanism for infection success." (PMID 37147351, 2023). "Accordingly, staining for the co-expression of CD74 and its co-receptors on T cells shows whether an infection with SARS-CoV-2 induce signaling in T cells." (PMID 37946732, 2023). "Interestingly, our results demonstrated that interaction scores of some paired ligands and receptors (e.g., ANXA1_FPR1, CD74_APP, CD74_COPA, CXCL1_CXCR1, CXCL2_CXCR2, and HLA-F_LILRB2) were significantly increased after infection." (PMID 37087411, 2023). "In agreement with our results in the experimental infection model, CD74 low monocytes were significantly enriched for the virus compared to CD74high monocytes, illustrating that also in this natural infection setting, CD74 expression can be used to enrich for monocytes carrying viral genomes." (PMID 31967545, 2020). "Based on our experimental infection results, we next tested whether CD74 expression on CD14+ monocytes could be used as a cell surface marker that will allow enrichment of cells that contain HCMV genomes in healthy seropositive individuals." (PMID 31967545, 2020). "Moreover, the conditioned environment generated by MIF/CD74 interaction in infected MDMs promotes CD4+ T-cell permissiveness to infection." (PMID 29997630, 2018). "The expression of genes related to basic composition of MHC-II like CD74 was up-regulated in CHv infected group which means the infection of CHv strain processes the potential to be presented to CD4+ cells and then evoke duck adaptive immune response in 24 hpi." (PMID 28903751, 2017). "Combination of CD74 and IP-10, illustrating both antigen presentation ability and response to type II interferon stimulation, may be representative of both faces of neonatal immunological competency to infection." (PMID 36509812, 2022). "As macrophages constitutively express CD74 the presence of the p41 invariant chain might block the activity of cathepsin B/L contributing to the resistance of hMDM to the infection by SARS-CoV and SARS-CoV-2." (PMID 33912475, 2021). "The strongest infection-induced interaction involved MIF signaling, where infected epithelial cells expressed MIF, which engage CD74/CD44 receptors on basal (Sq1A-B) and parabasal (Sq2B) bystanders." (PMID 41042872, 2025).
infection (continued). "The expression of C-C motif chemokine ligand 25 (CCL25), CD74, and cell division cycle 42 (CDC42) was also higher in SUS than RES lambs in response to challenge infection." (PMID 40811742, 2025). "With infection, L6 thrombocytes reduced the expression of their MHC II receptors (CD74 and BLB1) and decreased the expression of a core subunit of the mitochondrial respiratory chain complex 1 (MT-ND1)." (PMID 39880866, 2025). "Interaction between CD74 and MIF enhances the secretion of proinflammatory mediators and promotes unactivated CD4+ T cell infection, leading to viral spreading." (PMID 40427533, 2025). "The data indicated that the protein expression levels of MIF and CD74 in the spleen were downregulated in the infection group (p < 0.001), while levamisole and 25–100 mg/kg baicalin could increase CD74 protein level in the spleen compared to the infection group (p < 0.05)." (PMID 40427533, 2025). "In T. regenti-infected spinal cords, we recorded striking upregulation of Cd74, H2-Aa, H2-Ab1, and other members of the MHC II pathway throughout the infection." (PMID 35120185, 2022). "The majority of genes (CANX, B2M, CD74 and CTSB) in Antigen processing and presentation pathway were downregulated during infection." (PMID 33177569, 2020). "The expression of CD8a, CD74, and BCL6, which are regulators of MHC class II molecules and B-cell differentiation, was downregulated during early vvIBDV infection." (PMID 28086922, 2017). "Three weeks after infection, many unigenes were involved in adaptive immunity, including immunoglobulin IgG heavy chain, Fc receptor of IgE and CD8A antigen protein complex, CD74." (PMID 24886088, 2014). "By lethal infection with PR/8 virus, the expression level of FasL was dramatically increased in all cell types, especially in CD4(+), CD11c(+), CD74(+) or NK1.1(+) cells (light green color compared with orange color)." (PMID 23408968, 2013). "While the levels of most of the detected CD markers were not affected by ASFV infection, CD14 and CD74 levels significantly dropped after infection." (PMID 34835004, 2021). "In this case, the viral DNA and RNA levels in early stages of infection should be independent of CD74 cell-surface levels, and at later time points, higher load of virus leads to the observed differences in CD74 expression." (PMID 31967545, 2020). "Several lines of evidence suggest that this might be the case, based on the fact that CD74 expression is modulated in HIV-infected cells and that MIF plasma levels are elevated throughout the course of infection in HIV-infected subjects." (PMID 29997630, 2018). "Our results demonstrated that an increase in MIF expression due to infection was followed by a decrease in CD74 expression in the uterus from both non-pregnant and pregnant WT females." (PMID 29867817, 2018). "In order to quantitate CD44 and CD74 expression at different subcellular localization across all conditions, MFI cross-sectional quantifications corresponding to the regions encompassing only the plasma membrane or the cytoplasm, both for CD74 and CD44, were performed in all infection conditions." (PMID 29997630, 2018). "In response to MG, gene expression is up-regulated at the infection site in pathogen-recognition receptors (e.g. TLR1B), signalling molecules and their receptors (such as CXCL12 and IL17R), adaptive cell-surface receptors (CD74) and various other immunomodulators (e.g. ACOD1)." (PMID 38370402, 2024). "Moreover, CD74 is an indispensable part of the receptor complex of macrophage migration inhibitory factor (MIF), and macrophages can produce IL-8 that chemotactic leukocytes to the site of infection." (PMID 36405762, 2022). "Finally, we examined CD74 cell surface expression in infected and uninfected cells at different time points post infection but no major changes in CD74 distribution following infection were observed." (PMID 31967545, 2020).
infection (continued). "Thus, the aim of this work was to study the effect of MIF/CD74 interaction on the phenotype and the function of primary HIV-infected MDMs, and how this axis determines the environment to modulate CD4+ T-cell permissiveness to infection." (PMID 29997630, 2018). "This included increased transcriptional expression of the CD74 molecule MHC class II invariant (NP_001001613.1) which in mammalian species enables presentation of foreign peptides on cell surfaces to flag infection for T-cell response and demonstrated positive correlations with monocyte counts." (PMID 30518325, 2018). "Our results demonstrated that CD74 (full-length isoforms) expression was higher in pregnant MIF-/- females than in their WT counterparts, regardless of infection." (PMID 29867817, 2018).